IQCJ-SCHIP1 (IQCJ-SCHIP1 readthrough)
Description:
May play a role in action potential conduction in myelinated cells through the organization of molecular complexes at nodes of Ranvier and axon initial segments. May also play a role in axon outgrowth and guidance (By similarity).
Tractability: Antibody: its Gene Ontology location is reachable by antibodies, with medium confidence.
Gene: Protein-coding gene on chromosome 3 (158,962,235 to 159,897,358, forward strand). Ensembl gene ENSG00000283154.
Subcellular location: Cell projection, axon; Cytoplasm
Subcellular location (Human Protein Atlas): Cytosol
Gene Ontology:
Molecular function: protein binding
Biological process: negative regulation of cytoskeleton organization; positive regulation of hippo signaling
Cellular component: cytoplasm; axon initial segment; cell junction; plasma membrane; axon
Genetic constraint (gnomAD): Loss-of-function variants: 18 observed, 41.82 expected, observed/expected ratio (o/e) 0.43, 90% interval 0.3 to 0.64. The upper end of that interval is the gene's LOEUF score, 0.64, which puts it in group 2 of 6, group 1 being the genes least tolerant of losing a copy. Missense variants: 585 observed, 625.25 expected, observed/expected ratio (o/e) 0.94, 90% interval 0.87 to 1. Synonymous variants: 247 observed, 231.7 expected, observed/expected ratio (o/e) 1.07, 90% interval 0.96 to 1.18.